RN7SL15P (RNA, 7SL, cytoplasmic 15, pseudogene)
Gene: Miscellaneous RNA gene on chromosome X (41,345,576 to 41,345,876, reverse strand). Ensembl gene ENSG00000264573.
Homologues: Orthologues: chimpanzee Metazoa_SRP (99% identical), macaque Metazoa_SRP (94% identical). Paralogues in human: RN7SL1 (85% identical), RN7SL2 (84% identical), RN7SL3 (83% identical), RN7SL126P (82% identical), RN7SL408P (81% identical), RN7SL451P (81% identical), RN7SL778P (81% identical), RN7SL296P (81% identical), RN7SL804P (81% identical), RN7SL660P (80% identical), RN7SL186P (80% identical), RN7SL44P (80% identical), and 704 more.